HAUS1 (HAUS augmin like complex subunit 1)
Description:
Contributes to mitotic spindle assembly, maintenance of centrosome integrity and completion of cytokinesis as part of the HAUS augmin-like complex.
Synonyms: HEI-C; CCDC5; HEIC; HsT1461; FLJ40084
Tractability: PROTAC: ubiquitination databases record sites on it; its protein half-life has been measured.
Gene: Protein-coding gene on chromosome 18 (46,104,329 to 46,129,404, forward strand). Ensembl gene ENSG00000152240.
Subcellular location: Cytoplasm; Cytoplasm, cytoskeleton, microtubule organizing center, centrosome; Cytoplasm, cytoskeleton, spindle; Cytoplasm, cytoskeleton, spindle pole
Subcellular location (Human Protein Atlas): Cytosol; Centrosome; End piece; Mid piece
Pathways (Reactome):
Cell Cycle: AURKA Activation by TPX2; Loss of Nlp from mitotic centrosomes; Loss of proteins required for interphase microtubule organization from the centrosome; Recruitment of NuMA to mitotic centrosomes; Recruitment of mitotic centrosome proteins and complexes; Regulation of PLK1 Activity at G2/M Transition
Organelle biogenesis and maintenance: Anchoring of the basal body to the plasma membrane
Gene Ontology:
Molecular function: protein binding
Biological process: centrosome cycle; spindle assembly; regulation of microtubule nucleation
Cellular component: centrosome; cytosol; HAUS complex; mitotic spindle microtubule; cytoplasm; spindle; spindle pole
Genetic constraint (gnomAD): Loss-of-function variants: 13 observed, 16.92 expected, observed/expected ratio (o/e) 0.77, 90% interval 0.5 to 1.22. The upper end of that interval is the gene's LOEUF score, 1.22, which puts it in group 5 of 6, group 1 being the genes least tolerant of losing a copy. Missense variants: 185 observed, 188.76 expected, observed/expected ratio (o/e) 0.98, 90% interval 0.87 to 1.11. Synonymous variants: 61 observed, 68.14 expected, observed/expected ratio (o/e) 0.9, 90% interval 0.73 to 1.11.
Homologues: Orthologues: chimpanzee HAUS1 (100% identical), macaque HAUS1 (97% identical), rabbit HAUS1 (92% identical), dog HAUS1 (89% identical), pig HAUS1 (89% identical), guinea pig HAUS1 (87% identical), rat Haus1 (85% identical), mouse Haus1 (84% identical), tropical clawed frog haus1 (56% identical), zebrafish haus1 (41% identical).
Diseases named in the same sentence as HAUS1 in open-access papers:
HAUS1 is named in the same sentence as 8 diseases in open-access papers, as found by Europe PMC text mining. Sharing a sentence is not in itself a finding about the gene and the disease. The quoted sentences say what the papers report.
glioma (3 papers, 2022 to 2023). A benign or malignant brain and spinal cord tumor that arises from glial cells (astrocytes, oligodendrocytes, ependymal cells). "To further examine the underlying mechanisms of HAUS1 upregulation in glioma samples, we analysed the association between HAUS1 expression and its methylation." (PMID 35865089, 2022). "However, HAUS1 expression was higher and more significantly associated with OS in glioma (LGG and GBM) than in LIHC." (PMID 35865089, 2022). "However, little information is available regarding the association between HAUS1 expression and glioma risk and prognosis." (PMID 35865089, 2022). "Altogether, these results revealed that HAUS1 could serve as an independent prognostic risk factor for glioma." (PMID 35865089, 2022). "Based on the data retrieved from TCGA (703 samples) and CGGA (1018 samples), an elevated expression of HAUS1 was observed in glioma samples, which was associated with poorer survival of patients, unfavourable clinical characteristics, 1p/19q codeletion status, WHO grade, and IDH mutation status." (PMID 35865089, 2022). "Therefore, in this study, we mainly discussed the underlying mechanisms and biological functions of HAUS1 in patients with glioma." (PMID 35865089, 2022). "We compared the mRNA level of HAUS1 between normal and glioma tissue samples obtained from GTEx and TCGA databases." (PMID 35865089, 2022). "In this study, we discovered that the mRNA expression of HAUS1 was higher in glioma tissues than in normal tissues and increased with tumour grade." (PMID 35865089, 2022). "The pan-cancer analysis in this study revealed that HAUS1 expression was high in most cancers but only had a high statistical significance in the glioma tissue samples." (PMID 35865089, 2022). "The results revealed that HAUS1 had a higher mRNA expression level in glioma tissues than in normal tissues." (PMID 35865089, 2022). "In this study, we investigated the prognostic significance of HAUS1 mRNA expression and methylation in patients with glioma using data from the Chinese Glioma Genome Atlas (CGGA) and The Cancer Genome Atlas (TCGA) databases." (PMID 35865089, 2022). "A total of 22 types of TILs were screened using TCGA and CGGA samples, and their relationship with HAUS1 expression in patients with glioma was further assessed." (PMID 35865089, 2022). "A high tumour grade often predicted a worse prognosis, and the mRNA expression of HAUS1 increased with the malignant progression of glioma." (PMID 35865089, 2022). "Low expression of HAUS4 and HAUS6 and high expression of HAUS1, HAUS3, HAUS5, HAUS7, HAUS8 may be risk factors for poor prognosis in glioma patients." (PMID 37161065, 2023). "Furthermore, multivariate and univariate Cox analyses confirmed that HAUS1 is an independent prognostic factor for glioma." (PMID 35865089, 2022). "And the results showed that the expression level of HAUS1 plays a valuable role in glioma." (PMID 35865089, 2022). "HAUS1 was upregulated and served as a biomarker for poor prognosis in patients with glioma." (PMID 35865089, 2022). "Elevated HAUS1 expression (red and green) in the IDH1 mutation group indicated a dismal survival outcome, implying that HAUS1 was a significant prognostic factor for patients with glioma with the corresponding IDH1 genotypes (P < 0.001)." (PMID 35865089, 2022). "Therefore, we speculated that high HAUS1 expression stimulated tumour cell division and survival, thus exacerbating the malignant behaviour of glioma." (PMID 35865089, 2022). "However, the detailed expression pattern of HAUS1 and its correlation with immune infiltration in glioma (LGG and GBM) (LGG: low-grade glioma; GBM: glioblastoma) remain unknown." (PMID 35865089, 2022). "However, high HAUS1 expression was correlated with a poor OS in the patients with glioma." (PMID 35865089, 2022).
glioma (continued). "Furthermore, to assess whether HAUS1 could serve as a prognostic marker for glioma, we performed Kaplan–Meier survival analysis to compare the PFI, DSS, and OS of patients with glioma between the low- and high-HAUS1-expression groups." (PMID 35865089, 2022). "Therefore, we speculated that HAUS1 overexpression might be correlated with the malignant behaviour of glioma." (PMID 35865089, 2022). "Therefore, we investigated the relationship between HAUS1 and glioma." (PMID 35865089, 2022). "The research found that expression levels of the Augmin family genes HAUS1, HAUS3, HAUS4, HAUS5, HAUS6, HAUS7, and HAUS8 was all related with survival rates of glioma patients." (PMID 37161065, 2023). "The Kaplan–Meier curves demonstrated that the elevated HAUS1 expression was associated with a shorter OS, PFI, and DSS, and ROC curves demonstrated that HAUS1 might serve as an effective diagnostic biomarker for the differentiation of glioma from healthy tissues." (PMID 35865089, 2022). "A total of 325 and 693 glioma samples from the CGGA database and 749 glioma samples from TCGA database were used to assess the relationship between HAUS1 overexpression and malignant behaviour of glioma." (PMID 35865089, 2022). "First, we did not further explore and verify the functional role of HAUS1 in the immune microenvironment of glioma." (PMID 35865089, 2022). "The high expression level and positive prognostic value of HAUS1 in glioma (LGG and GBM) suggested that patients with LGG and GBM might be eligible candidates for anti-HAUS1 immunotherapy." (PMID 35865089, 2022).
hepatocellular carcinoma (2 papers, 2024 to 2025). A malignant tumor that arises from hepatocytes. "Although our research has evaluated the significance of HAUS1 in HCC from the aspects of immune microenvironment, growth, prognosis, etc, but there are still some deficiencies, and the mechanism of HAUS1 affecting the development of hepatocellular carcinoma cells needs to be further studied." (PMID 38356703, 2024). "Interference with the expression of HAUS1 would block the cell cycle in G0/G1 and S phases, and increase the apoptosis of hepatocellular carcinoma cells." (PMID 38356703, 2024). "Subsequently, we separately analyzed the expression of HAUS1 in HCC and paired and unpaired samples using the TCGA database, and found that the expression of HAUS1 increased in LIHC (Liver hepatocellular carcinoma)." (PMID 38356703, 2024). "Although HAUS1 has been intensively studied, but its significance and relationship with the immune microenvironment in Hepatocellular carcinoma (HCC) remain unclear." (PMID 38356703, 2024).
retinal disease (1 paper, 2012). "Based on putative function and/or involvement in retinal disease, we selected 16 genes – Bach2, Cdr2, Dusp12, Esrrb, Gpsm2, Haus1, Kdm5b, Lman1, Lrp11, Lrrc2, Ncoa2, Plekha2, Ppargc1b, Trim36, Wisp1 and Zdhhc14." (PMID 22511886, 2012).
cancer (4 papers, 2012 to 2024). A tumor composed of atypical neoplastic, often pleomorphic cells that invade other tissues. "Subsequently, we used GEPIA2 to evaluate the expression level of HAUS1 in pan cancer and found that HAUS1 expression was significantly high in DLBC, GBM, LGG, LIHC, PAAD, SKCM, TGCT, and THYM." (PMID 35865089, 2022). "Owing to the overexpression of HAUS1, we further evaluated its prognostic significance in these cancers." (PMID 35865089, 2022). "Moreover, HAUS1 interference suppresses the invasion ability of cancer cells." (PMID 38356703, 2024). "The expression of HAUS Augmin-like complex subunit 1 (HAUS1), a protein-coding gene, is low in normal samples among various cancers with pan-cancer analysis." (PMID 35865089, 2022). "Furthermore, HAUS1, a component of the augmin complex involved in spindle microtubule generation in mitosis and TSPAN8 (also known as CO-029), that encodes for an integrin-binding glycoprotein that stimulates endothelial cell proliferation, are also up-regulated in cancer patients." (PMID 23009291, 2012).
tumor (3 papers, 2022 to 2024). "HAUS1 expression level was associated with several tumour-infiltrating immune cells, such as Th2 cells, macrophages, and activated dendritic cells." (PMID 35865089, 2022). "To assess the underlying mechanisms of HAUS1 in promoting tumour progression, we screened for DEGs in the low- and high-HAUS1-expression groups." (PMID 35865089, 2022). "High HAUS1 expression was associated with several tumour-infiltrating immune cells such as Th2 cells, macrophages, and activated dendritic cells, which had high infiltration levels." (PMID 35865089, 2022). "Current evidence suggested that HAUS1 was closely associated with tumor formation and might contribute to tumor progression." (PMID 38356703, 2024). "In addition, the HAUS1 promoter methylation modification was analysed using MEXPRESS, and the association between HAUS1 expression and tumour-infiltrating immune cells was investigated using CIBERSORT." (PMID 35865089, 2022). "At the same time, Cox regression analysis identified several factors that significantly influence the survival of HCC patients, including T stage, M stage, histopathology stage, tumor status, and HAUS1 expression." (PMID 38356703, 2024). "Immune cells were significantly enriched in tumor tissues with high HAUS1 expression, and infiltration was also increased." (PMID 38356703, 2024). "In HCC tumor tissues with high HAUS1 expression, the immune microenvironment might shift from activated effector cells to quiescent immune inhibitory cells." (PMID 38356703, 2024). "In multivariate analysis, only tumor state and HAUS1 expression are important predictors of patient survival, So HAUS1 could serve as a superb independent prognostic factor for HCC." (PMID 38356703, 2024). "However, the role of HAUS1 in tumours remains unclear, especially, its relationship with immune infiltration and TME." (PMID 35865089, 2022). "In addition, we investigated whether the tumour-immune microenvironment was different between patients with elevated HAUS1 expression and those with low-HAUS1 expression." (PMID 35865089, 2022).
HAUS1 also shares sentences with these, for which no sentence is quoted: glioblastoma (1 paper); low grade glioma (1); myelodysplastic syndrome (1).